CFHR1 (complement factor H related 1)
Diseases named in the same sentence as CFHR1 in open-access papers (continued):
Sharing a sentence is not in itself a finding about the gene and the disease.
cancer (8 papers, 2016 to 2023). A tumor composed of atypical neoplastic, often pleomorphic cells that invade other tissues. "Gamma-glutamyl hydrolase and CFHR1 were the most strongly upregulated proteins in the TC group, with ratios (cancer/control) of 4.669 and 7.799, respectively." (PMID 32704452, 2020). "In the screening experiment, we found that CFHR1 exhibited the highest fold-change (cancer/control) among the differentially expressed proteins." (PMID 32704452, 2020). "A significant difference in CFHR1 levels was found among the five groups, and CFHR1 concentrations were higher in the cancer groups compared to that in the control group." (PMID 32704452, 2020). "Levels of keratins, type I cytoskeletal 16 (KRT16), 9 (KRT9), and 10 (KRT10), as well as complement factor H‐related protein 4 (CFHR4) and 1 (CFHR1), had higher levels in plasma samples from patients with cancer in the right colon (with fold changes between 6.2‐13.0)." (PMID 32452655, 2020). "The top three proteins, KRT16 (with a fold change of 45.6), CFHR4 (with a fold change of 41.2), and CFHR1 (with a fold change of 27.9), all displayed higher plasma levels in samples from patients with stage III cancer in the right colon than the rectum." (PMID 32452655, 2020). "Additionally, CNV analysis identified amplification of PNP, FCGR3A, and CFHR1 as well as deep deletion of ETV6, CFHR1, and RPS15 as the most frequently detected copy number altered PID-related genes across the four available pediatric cancer cohorts." (PMID 36497424, 2022).
infection (7 papers, 2012 to 2024). The state of being infected such as from the introduction of a foreign agent such as serum, vaccine, antigenic substance or organism. "CFHR1 deletion has been reported to be associated with renal disease in an incomplete penetrance and a second hit such as infection is considered to be essential for disease development." (PMID 32636836, 2020). "In this study, we extend the characterization of molecular interaction of CFH/CFHR proteins and show that the infection-associated CRASP-4/ErpC protein of B. burgdorferi binds the host complement regulators CFHR1, CFHR2, and CFHR5, and to some extent CFH." (PMID 22400034, 2012). "Future studies should focus on the use of P. aeruginosa Cfhr-1 knock-out mice model of infection to evaluate the role of FHR-1 in vivo." (PMID 38510967, 2024). "It is unknown whether CFHR1 homozygous deletion alone would trigger the onset of these conditions upon infection." (PMID 32636836, 2020). "There is no report on CFHR1 gene knockout in any animal infection model and its function in vivo is still unclear." (PMID 32636836, 2020).
kidney disease (6 papers, 2011 to 2026). "Importantly, three recent reports showed that CFHR1, CFHR2, and CFHR5 deregulate complement by competing with FH for binding to C3b, and thus they may rather enhance complement activation in human renal diseases." (PMID 25855355, 2015).
genetic disorders (1 paper, 2012). "In this study, we found that in 45 children diagnosed with aHUS, genetic disorders in complement-regulating genes encoding CFH, CFI, MCP, CFB, C3, and THBD, as well as the presence of αFH with or without a homozygous deletion in CFHR1/3, are linked with clinical presentation, treatment, and outcome." (PMID 22410797, 2012).
infectious disease (1 paper, 2022). A disorder directly resulting from the presence and activity of a microbial, viral, or parasitic agent in humans. "For instance, CFHR1 is induced in COVID‐19, but suppressed in MPX, reflecting the different roles of the complement system in the two infectious diseases." (PMID 36169042, 2022).
CFHR1 also shares sentences with these, for which no sentence is quoted: end stage renal disease (4 papers); Stroke (4); lung carcinoma (3); pulmonary fibrosis (3); acute myelogenous leukemia (2); COVID-19 (2); dense deposit disease (2); glomerular diseases (2); myocardial infarction (2); ovarian carcinoma (2); Alexander disease (1); allergic asthma (1); Amoebiasis (1); anemia (1); asthma (1); Atrophy (1); autism (1); autosomal dominant polycystic kidney disease (1); bacterial infections (1); C3 glomerulonephritis (1); cardiovascular disease (1); cataract (1); cervical carcinoma (1); chronic central serous chorioretinopathy (1); cognitive decline (1); coronary artery disease (1); depression (1); diabetes (1); Diffuse mesangial sclerosis (1); dilated cardiomyopathy (1).
A further 32 diseases each share a sentence with CFHR1 in 1 paper.